RNU1-129P (RNA, U1 small nuclear 129, pseudogene)
Synonyms: RNU1-137P
Gene: Small nuclear RNA gene on chromosome 1 (148,014,417 to 148,014,583, reverse strand). Ensembl gene ENSG00000206791.
Homologues: Orthologues: macaque U1 (77% identical), dog U1 (65% identical), guinea pig U1 (62% identical), rabbit U1 (60% identical), dog U1 (59% identical), rabbit U1 (59% identical), dog U1 (58% identical), rabbit U1 (58% identical), dog U1 (57% identical), dog U1 (55% identical), rabbit U1 (53% identical). Paralogues in human: RNU1-154P (99% identical), RNU1-114P (84% identical), RNU1-1 (68% identical), RNU1-2 (68% identical), RNU1-27P (68% identical), RNU1-28P (68% identical), RNU1-3 (68% identical), RNU1-4 (68% identical), RNVU1-18 (68% identical), RNVU1-29 (68% identical), RNVU1-31 (68% identical), U1 (68% identical), and 133 more.